CD4 (CD4 molecule)
Diseases named in the same sentence as CD4 in open-access papers (continued):
Sharing a sentence is not in itself a finding about the gene and the disease.
fungal infections (continued). "Notably, the frequency of interleukin-17–producing CD4+ T cells (Th17 cells) which play a key role in antifungal immunity, was within normal limits in this patient, suggesting that her susceptibility to fungal infections was likely not due to Th17 cell deficiency." (PMID 40977680, 2025). "The virus is known to cause immune dysregulation, an overproduction of pro-inflammatory cytokines, a weakened cell-mediated immunity, and a decrease in CD4 and CD8+ T-cells, all of which can increase the likelihood of invasive fungal infections." (PMID 37764170, 2023). "CD4+ T cell, as antigen presenting cell and CD8+ T cell, as a cytotoxic cell constitute an important immune defense barrier against fungal infection." (PMID 36707667, 2023). "The CD4+ T cells in the peripheral blood were collected from active IBD patients and healthy controls following different doses of fungi infection." (PMID 37124046, 2023). "The importance of CD4+ T lymphocytes producing IFN-γ and IL-17 to control fungal infection was observed, for instance, in models of infection by Pneumocystis, H. capsulatum, Cryptococcus neoformans, P. brasiliensis, Candida albicans, and A. fumigatus." (PMID 34359982, 2021). "CD4+ TH1 and TH17 cell-mediated immunity plays important roles in host defense against fungal infection." (PMID 32765468, 2020). "Elevation of CD4 and CD8 levels in the FI group after fungal challenge suggests that CD4 and CD8 T cells play a key role in fungal infections on skin tissues." (PMID 31579583, 2019). "In general, the CD4+ T cells by secreting the cytokines IFN-γ, TNF-α, and IL-17A determine host resistance to severe fungal infections, such as paracoccidioidomycosis, coccidioidomycosis, aspergillosis and candidiasis." (PMID 29520092, 2018). "Several immune cell types including CD4+ (Th17), CD8+ T (Tc17) cells, NK cells, iNKT cells, γδT cells, B cells, ILCs, DCs, and neutrophils have been shown to produce IL-17 during fungal infection." (PMID 29403476, 2017). "When CD4+ T cell counts are low, as in patients with AIDS, CD8+ T cells have a heightened role in controlling fungal infections." (PMID 29358941, 2017). "Although CD4+ T cells play a major role in fungal control, mediation of protective immunity by CD8+ T cells against fungal infection has been documented." (PMID 28694566, 2017). "CD4+ and CD8+ T-cells, NK cells, γδT cells, and neutrophils have been shown to produce IFNγ during fungal infection." (PMID 29403476, 2017). "A second limitation of the study is that we are not able to determine a reason for the difference in the phenotypic response of CD4 and CD8 T cells during fungal infection." (PMID 26786705, 2016). "We believe that idiopathic CD4+ lymphocytopenia is an important etiologic factor to be considered for patients who present with mass lesions and are diagnosed by FNA with atypical fungal infections." (PMID 20806085, 2010). "We and others have previously shown that effector CD8+ T cells were elicited in the absence of CD4+ T cells and compensated CD4+ T cells for vaccine-induced immunity to fungal infections." (PMID 40491915, 2025). "Despite not inhibiting interleukin-2-inducible kinase critical for CD4 T-cell signaling, cases of disseminated fungal infections have also been documented with this agent." (PMID 40421329, 2025). "On the other hand, in a fungal infection model of mouse ear skin, CD4+ TRM cells did not form clusters, but were instead scattered and colocalized with MHC-II+ APCs." (PMID 40791604, 2025). "Hence, fungal infections remain a major concern in PLHIV, particularly among those with low CD4+ counts." (PMID 40943696, 2025). "CD4+ TFH primary function is to provide protection against pathogens by providing critical signals to B cells which allows them to undergo high-affinity selection and development of B memory cells (BM) against viral, bacterial, parasite and fungal infections." (PMID 39328410, 2024).
fungal infections (continued). "In contrast, early CD4+ T cell activation increased in the spleens of both fungal infection groups, with no discernible difference between them." (PMID 37211685, 2023). "Studies have shown that mice lacking T cells exhibited high mortality after a fungal infection with a small inoculum, proving the importance of CD4+ and CD8+ T cells in the effectiveness of the immune response against this pathogen." (PMID 36836308, 2023). "CD8 T cells become crucial and immunologically vital for suppressing fungal infections, especially when CD4 T cells are absent or perhaps have relatively low concentrations." (PMID 36985244, 2023). "In addition, both CD4+ and CD8+ T cells are necessary to prevent the reactivation of certain fungal infections." (PMID 34880863, 2021). "We then analyzed the possible factors, including the levels of IgA, IgG, IgM, as well as CD4/CD8 T cell, NK cell, T cell, and B cell counts, to clarify whether these factors were correlated with a fungal infection." (PMID 29552004, 2018). "There is no doubt that CD4+ T cells play a major role in mediating resistance against fungal infection in immunocompetent and immunosuppressed patients." (PMID 28694566, 2017). "Fungal infections have skyrocketed in immune-compromised patients lacking CD4+ T cells, underscoring the need for vaccine prevention." (PMID 26367276, 2015). "Moreover, the importance of CD4+ and CD8+ T cells in eliciting host immune response during fungal infections are well recognized." (PMID 25201772, 2014). "Previous studies have shown that CD4+ T-cell responses are critical for protection from invasive fungal infections (IFIs), whereas CD8+ T cells have not been examined." (PMID 23883548, 2013). "Thus, for the purpose of immunotherapy and vaccine design, the inherent plasticity of CD4+ T helper cell subsets will require careful analysis, not only in autoimmune conditions but also in the context of fungal infections." (PMID 31813764, 2020). "Decreases in WBC and CD4 T-cell counts have been reported during the acute phase of SFTS, and it is possible that the complication of invasive fungal infection observed in our case-patients may be explained, at least in part, by SFTSV-induced immunosuppression during the acute phase." (PMID 27776187, 2016). "Missing from the development of this evolving paradigm are the ontogeny of CD4+ T cells, monocytes, NK cells, and their activation among patients who resolved their infections successfully with antifungal therapy and ART and those who died early in the course of this fungal infection." (PMID 25492918, 2015). "And for those patients whose preoperative CD4 counts ≤ 200 cells/μ L, the antibiotic and antifungal medications (sulfamethoxazole/trimethoprim (SMZ/TMP) and fluconazole) are started preoperatively as prophylaxis against Pneumocystis carinii pneumonia (PCP) and fungal infection." (PMID 22583551, 2012). "C. albicans gDNA uniquely promotes Treg induction while preserving CD4+ T cell viability in an inflammatory milieu (IL-2 + TGF-β stimulation) or in splenocytes, suggesting that its DNA may help counterbalance T cell exhaustion and inflammation induced by fungal infection." (PMID 41295141, 2025). "However, in multivariate time-varying Cox models, after controlling for immune and virologic parameters over time and non-PCP fungal infections, baseline CD4+ T-cell count, CD4+ percentage, and HIV RNA levels were predictors of IRIS, consistent with previous research." (PMID 20617176, 2010). "In the absence of CD4+ T cells, CD8+ T cells also play a major role in controlling fungal infection." (PMID 29358941, 2017). "Herein, we describe a specific role for Dectin-1 in controlling CD4+, but not CD8+, T-cell responses and survival during fungal infection in the GI tract." (PMID 26349660, 2016).
fungal infections (continued). "The presence of low baseline CD4+ T-cell count and high HIV RNA levels, a non-PCP fungal infection, and improved immunologic and virologic response to ART predict the development of IRIS." (PMID 20617176, 2010). "In patients with advanced immunosuppression and non-tuberculous OIs, the presence of a fungal infection, lower CD4+ T-cell counts and higher HIV RNA levels at baseline, and higher CD4+ T-cell counts and lower HIV RNA levels on treatment are associated with IRIS." (PMID 20617176, 2010).
allergic asthma (142 papers, 2005 to 2025). A asthma with a basis in a pathological type I hypersensitivity reaction. "Next, we used a conditional knockout (CKO) strategy and observed that the loss of CD226 in CD4+ T cells alleviated ovalbumin (OVA)-induced allergic asthma in mice, and CD226 played a critical role in regulating CD4+ T cell apoptosis." (PMID 39349422, 2024). "We found that CD226 deficiency in CD4+ T cells mitigated lung inflammation, IgE production, and eosinophil infiltration and reduced airway remodeling in experimental allergic asthma." (PMID 39349422, 2024). "This demonstrated an association in low PD-1 expression by circulating CD4+ T cells and serum IgE concentrations in allergic asthma, with little change in the regulation of PD-L1 and PD-L2." (PMID 34769327, 2021). "In 2016, another study indicated that neonatal gut microbiota dysbiosis led to CD4 + T cell dysfunction associated with childhood atopy, which affected the susceptibility of allergic asthma in children." (PMID 35002992, 2021). "CD4+ cells are predominantly associated with allergic asthma and eosinophils, MCs, and basophils with airway inflammation." (PMID 34769327, 2021). "Hypogammaglobulinemia E in adults with IgGSD was negatively associated with bronchitis, allergic asthma, IgG1, and levels of blood CD4 + lymphocytes, after adjustment for other variables." (PMID 34372773, 2021). "Both in humans and in experimental animals, CD4+ T-helper (Th) lymphocytes central to the pathogenesis of allergic asthma have been extensively studied and, yet, the underlying mechanisms of this relapsing-remitting disease remain incompletely understood." (PMID 31105692, 2019). "Taken together, these results demonstrate that the removal of Bcl11b from mature T-cells results in reduced pulmonary pathology after induction of allergic asthma, which was associated with reduced lung eosinophils and CD4+ T-cells." (PMID 29700302, 2018). "In murine models of allergic asthma, IL-17 expression is most often associated with CD4+ T cells, although γδ T cells and macrophages can also express IL-17." (PMID 25123451, 2014). "Ovalbumin (OVA) is widely used as a reference allergen to induce allergic asthma, which can cause the imbalance of CD4+ T lymphocytes, secretion of cytokines, and immune inflammation." (PMID 23970934, 2013). "IL-9 is produced by CD4 + T cells, in particular Th2 cells, and is associated with allergic asthma." (PMID 39061002, 2024). "Allergic asthma is caused primarily by an inappropriate CD4+ Th2 response, which results in symptoms mediated by Th2 cytokines, including IL-13 provoking airways hyperresponsiveness and mucus production, IL-4 promoting the production of antigen specific IgE, and IL-5 inducing eosinophilia." (PMID 20659336, 2010). "Wnt10b deficiency mice of allergic asthma results in enhanced memory T cell activation, increased Th2 polarization as evidenced by elevated IL-4 and IL-13 concentrations, and recombinant Wnt10b increases the percentage of naïve CD4+T and CD8+T cells in vitro, thereby mitigating allergic asthma." (PMID 40433386, 2025). "An integral element of these studies was to assess the effect of MMF and TFB on the CD4+ T-cell mediated immune response in the MLNs and lungs, i.e., in the inductive and effector sites, respectively, of the immune response underlying the development of allergic asthma." (PMID 39598682, 2024). "In this study, macrophages transfected with emu-miR-10a-5p tended to induce naïve CD4+ T cell differentiation to Th1 cells, and emu-miR-10a-5p tended to reverse the Th1/Th2 balance in mice with allergic asthma, consistent with our in vitro results." (PMID 40496853, 2025). "In ovalbumin-induced allergic asthma mouse models, IL-7 signaling has been shown to be necessary for the survival of allergen-specific CD4 + T cells." (PMID 39806440, 2025).
allergic asthma (continued). "Together, these findings suggest a model in which CGRP alleviates allergic asthma primarily through RAMP1-mediated regulation of CD4+ T cells during the sensitization phase." (PMID 41472747, 2025). "Compared to the control group, the allergic asthma group exhibited a higher abundance of resting NK cells, whereas the proportions of naive CD4 T cells and activated NK cells were lower." (PMID 41458997, 2025). "Studies have shown that HMGB1 can influence CD4+ T cell differentiation, mediating inflammatory responses in conditions of allergic asthma." (PMID 40842957, 2025). "In this study, we revealed a previously unappreciated role for the CGRP–RAMP1 pathway in suppressing CD4+ T cell activation and restraining Tfh cell accumulation during the sensitization phase of allergic asthma." (PMID 41472747, 2025). "This illustrates that DMF exerts protective effects in allergic asthma via upregulation of Nrf2, whereas CD4-specific deletion of Nrf2 exacerbates the inflammatory response in allergic asthma." (PMID 38711519, 2024). "This study demonstrated the regulatory role of CD226 in allergic asthma by modulating the apoptosis of CD4+ T cells." (PMID 39349422, 2024). "Our study showed upregulation of oxidative stress in CD4+ T cells in mice with allergic asthma as depicted by upregulated iNOS and nitrotyrsoine in CD4+ T cells." (PMID 36144198, 2022). "Type 2-associated innate immune receptors, including ST2 (IL-33 receptor) and IL17RB (IL-25 receptor), were highly expressed on allergen-specific CD4 T cells from the BALF of patients with allergic asthma after an allergen challenge." (PMID 36591273, 2022). "IL-4 was produced by CD4 T cells stimulated by antigen or mitogen, which was closely related to the occurrence of allergic asthma." (PMID 35431951, 2022). "These IL-17-producing memory CD4 T cells were reported to develop from allergen-specific memory Th2 cells after stimulation by proinflammatory cytokines, and to aggravate allergic asthma upon allergen re-exposure in mice and humans." (PMID 36591273, 2022). "LAG3, an MHC-class-II-binding CD4+ homologue has been identified to suppress airway inflammation in a mouse model of OVA-induced allergic asthma." (PMID 36067164, 2022). "Not only this but we also found for the first time that more dual-positive Th2–Th17 cells can be obtained by conditioned differentiation of mouse CD4+ T cells after classical allergic asthma modeling." (PMID 34394777, 2021). "The results indicate that none of all the tested therapeutic strategies showed the potential to counteract the development of allergic asthma by increasing the production of IL-10 by CD4+ T cells other than Treg ones." (PMID 34071080, 2021). "Lung inflammation in allergic asthma is orchestrated by activation of CD4+ T lymphocytes to stimulate the release of inflammatory mediators and elicit eosinophilia." (PMID 34440118, 2021). "Similar to the case in the mRNA expression level of IL-5 and IL-13 in allergic asthma, the percentages of IL-5+ and IL-13+ CD4+ Th cells were significantly lower in HDM-sensitized Tlr9−/− mice than in HDM-sensitized WT mice." (PMID 33093516, 2020). "Enhanced production of Th2 effector CD4+ T cells and their signature cytokines (e.g. IL-4, IL-5, IL-13) are a major contributor to allergic asthma in humans." (PMID 33424845, 2020). "The differentiation of CD4+ lymphocytes Th17/regulatory T cells (Treg) and indoleamine 2,3-dioxygenase (IDO) is associated with the pathogenesis of allergic asthma." (PMID 32834826, 2020). "The populations of Th17 cells (CD4+ RORγt+ IL17z+) and Tregs (CD4+ CD25+ Foxp3+) among peripheral PBMCs were examined using flow cytometry for both the allergic asthma and healthy control groups." (PMID 32834826, 2020). "Characteristic of allergic asthma, CD4+Th2 lymphocytes secrete Th2 cytokines, interleukin (IL)-4, IL-13, and IL-5 that mediate the inflammatory immune response." (PMID 32477356, 2020).
allergic asthma (continued). "The specific binding of Salp15 to CD4 inhibited the proliferation and differentiation of CD4+ T cells toward Th2 cells and suppressed the production of inflammatory cytokines, significantly reducing symptoms of allergic asthma in treated mice." (PMID 33072132, 2020). "Although allergic asthma was Th2-dominated, Th1 and other CD4+ T subpopulations were also involved in the initiation and aggravation of disease." (PMID 31231429, 2019). "In this study, to develop a cellular therapy for allergic asthma, we converted naive CD4+ T cells to OVA-specific DNT cells ex vivo." (PMID 31534137, 2019). "Long-lived allergen-specific memory CD4+ T helper 2 (Th2) cells in mice persist in lungs for more than 2 years after the induction of experimental allergic asthma (EAA)." (PMID 31105692, 2019). "And PD-L1+ mast cell is a negative regulator of conventional CD4+ T cells, and understanding of the role will give propulsion to the development of novel therapeutic approaches in allergic asthma." (PMID 30808413, 2019). "EGR2 has been shown to be a crucial mediator of allergic asthma, as its expression is necessary in mast cells to direct CD4+ T cell migration to inflamed lung." (PMID 31832069, 2019). "Here, we show that deletion of the Ifitm family biases CD4+ Th differentiation to Th1 and reduces the severity of allergic airways disease in a murine model of allergic asthma." (PMID 30365177, 2019). "Despite the high efficacy of AOS, little is known about the changes of IL-10, TGF-β, Th1, and Th2 cytokines, and CD4+CD25highCD127low Treg cells in the children with allergic asthma." (PMID 30294594, 2018). "The results suggest AOS consumption reduces the risk of allergic asthma by increasing the percentage of CD4+CD25+ T cells, CD4+CD25high, CD4+CD25+FoxP3+ Treg cells and CD4+CD25highCD127low Treg cells in PBMCs." (PMID 30294594, 2018). "CD4+ T cells expressing CCR4 have thus been of particular interest in the pathogenesis of allergic asthma." (PMID 29507584, 2018). "Allergic asthma is a prototype of type 2 immunity, orchestrated by an aberrant adaptive CD4+ T helper 2 (Th2) cell immune response to airborne allergens such as house dust mite (HDM)." (PMID 29444897, 2018). "Analyses of childhood allergic asthma by using CD4+CD25highCD127low Treg cells will have important clinical values." (PMID 30294594, 2018). "Xue and Shi investigated the number and functional role of CD4+ CD25+ TRegs in the PBMCs of patients with allergic asthma." (PMID 31826046, 2018). "It has been shown in numerous investigations that IFN-γ can suppress the proliferation of Th2 type CD4+ T-cells and it has been shown to inhibit the infiltration of CD4+ cells into the airways in a mouse allergic asthma model." (PMID 28399855, 2017). "In accordance with our results, previous studies showed the therapeutic potentials of helminths in resistance from allergic asthma via the expansion of CD4+CD25+FOXP3+ regulatory cells and IL-10 and TGF-β production." (PMID 28494800, 2017). "As previously shown, transfer of 5 × 106 polyclonal, in vitro expanded CD4+CD25+ Tregs successfully suppressed airway inflammation in an allergic asthma model, whereas a 10-fold lower number of allergen-specific Treg cells were needed for the similar effect." (PMID 28955341, 2017). "Purified CD4+ T cells were separated from PBMCs of children with allergic asthma, and were stimulated with plate-coated anti-CD3 in the presence or absence of 20 ng/ml IL-9 for 3 days, the concentration of IFN-γ in the supernatants were then detected by ELISA." (PMID 28724400, 2017). "On the contrary, regulatory T cells (Tregs) constitute a subpopulation of CD4+ T cells that has been involved in controlling the magnitude of the immune response against environmental antigens during allergic asthma." (PMID 28066430, 2016).